FAM246A (family with sequence similarity 246 member A)
Gene: Protein-coding gene on chromosome 22 (21,360,601 to 21,361,299, reverse strand). Ensembl gene ENSG00000286102.
Homologues: Orthologues: mouse Fam246a (72% identical), rat LOC120095536 (70% identical). Paralogues in human: FAM246B (98% identical), FAM246C (43% identical).